TRH (thyrotropin releasing hormone)
Diseases named in the same sentence as TRH in open-access papers (continued):
Sharing a sentence is not in itself a finding about the gene and the disease.
depression (38 papers, 1997 to 2025). "One mechanism explaining the increase in T4 seen in depression is the activation of hypothalamic TRH producing neurons and subsequent increase in thyroid function secondary to the rise in cortisol associated with depression." (PMID 22220285, 2012). "Thyrotropin-releasing hormone-(TRH) has been shown to have antidepressant properties, and TRH-1 and -2 receptor deficient mice display an increased depression-like behavioral phenotype." (PMID 21886553, 2011). "Furthermore, higher TRH concentrations have consistently been reported in the cerebrospinal fluid of individuals with depression, indicating that depression is associated with a changed TRH response." (PMID 36003348, 2022). "Depression causes a blunted TSH response to thyrotropin-releasing hormone (TRH) stimulation and the expected nocturnal rise in TSH may be absent or diminished." (PMID 21750631, 2011). "For instance, individuals with major depression have been observed to exhibit a diminished thyroid-stimulating hormone (TSH) response to thyrotropin-releasing hormone (TRH) stimulation and a reduced nocturnal TSH surge." (PMID 39749022, 2024). "Throughout episodes of depression, the hypothalamus releases greater thyrotropin-releasing hormone (TRH), which raises serotonin levels in the brain." (PMID 36811059, 2023). "Several studies have shown that compared to HCs, TSH response to TRH were blunted in patients with depression." (PMID 34721116, 2021). "Fortunately, TRH has been proved effect in improving depression, memory impairment and regulating sympathetic nervous system." (PMID 30555300, 2018). "Administration of TRH at a dose of 500 μg parenterally to unipolar depressed women led to a significant improvement in depression ratings." (PMID 22220285, 2012). "Previous studies have evidenced that pituitary response to TRH is blunted in a number of psychiatric conditions, including schizophrenia, bipolar disorders, alcoholism and depression." (PMID 21569245, 2011). "BD depression patients showed a higher TRH-TSH response compared to BD mania subjects." (PMID 40895630, 2025). "Exploring the elevation of TSH, the TRH (Thyrotropin-Releasing Hormone) hypothesis of depression posits that decreased 5-HT function leads to increased TRH secretion, maintaining normal thyroid hormone levels." (PMID 39119074, 2024). "Further research could illuminate the significant role of central TRH in NSSI behaviors among adolescents with depression." (PMID 39119074, 2024). "According to the TRH hypothesis of depression, chronic TRH hypersecretion in depression can be a compensatory mechanism to normalize serotonin (5-HT) function." (PMID 37469355, 2023). "It has been observed that TRH is involved in the regulation of thermogenesis, feeding behavior and water intake, and it can play a role in the pathophysiology of major depression disorder." (PMID 36147745, 2022). "pGluAP has TRH as a substrate and produces the antioxidant and anti-inflammatory histidyl-proline diketopiperazine (cyclo [His-Pro]; cHP) as a product, but both exert effects on the CNS that include excitement and depression." (PMID 34836194, 2021). "On the other hand, reduced intracerebral serotonin concentration in depression could lead to increased TRH concentration in brain tissues." (PMID 28882111, 2017). "The prolonged release of TRH in depression may be seen as a compensatory response to the decreased 5HT activity in an attempt to normalize 5HT function and maintain normal levels of thyroid hormones." (PMID 22220285, 2012). "Furthermore, TRH-R1 knockout mice showed increased anxiety and depression-like behavior thus supporting a role for endogenous TRH in mood regulation." (PMID 22220285, 2012). "A sub-clinical dysfunction of axis thyrotropin releasing hormone (TRH) thyroid stimulating hormone (TSH) with consequent alteration of circadian rhythms of TSH has been hypothesized in several depressive disorders." (PMID 16285879, 2005).
depression (continued). "A sub-clinical dysfunction of axis Thyrotropin Releasing Hormone (TRH) – Thyroid Stimulating Hormone (TSH) with consequent alteration of circadian rhythms of TSH has been hypothesized in some depressive disorders." (PMID 15317653, 2004). "The reasons and mechanisms for this phenomenon may be as follows: First, the concentration of 5-hydroxytryptamine in the brain is reduced in patients with major depression, leading to an increase in the concentration of thyrotropin-releasing hormone (TRH), which accelerates the secretion of TSH." (PMID 37008928, 2023). "In addition, it was hypothesized that the elevation of cortisol levels often found in depression could inhibit the effect of TRH on TSH." (PMID 34887837, 2021). "Furthermore, an attenuated TSH response to TRH has been found in patients with depression." (PMID 31795239, 2019). "Electroconvulsive therapy, which is an effective treatment of depression, increases TRH gene expression in the brain, and the CART system regulates TRH activity." (PMID 21886553, 2011). "Previous studies have shown that patients with psychotic depression have a considerably lower response to thyrotropin-releasing hormone stimulation compared with patients without psychotic symptoms." (PMID 38262974, 2024). "The levels of TSH as well as TSH responses to thyrotropin - releasing hormone (TRH) have been described to be different in healthy controls compared to patients with psychiatric disorders, including major depression, bipolar mania, alcoholism, and borderline personality disorder." (PMID 30055589, 2018). "In our population, changes in hormonal responses to APO and TRH tests do not appear to be significantly influenced by the severity or subtype of depression, number of suicide attempts, violence of method or HPA axis activity (as evaluated by post-DST cortisol levels)." (PMID 35625008, 2022). "Additionally, since no TRH analogs has been approved to date for the treatment of depression, the use of DA agonist agents—via stimulation of the TRH-compensatory mechanism—could represent a new therapeutic approach for suicide prevention." (PMID 35625008, 2022).
Obesity (32 papers, 2014 to 2025). Accumulation of substantial excess body fat. "Leptin levels rise with obesity, causing thyrotropin-releasing hormone (TRH) production in the paraventricular nucleus of the hypothalamus." (PMID 35047272, 2021). "Alternate mechanism indicating obesity leading to increased leptin levels which stimulate hypothalamus causing increased TRH secretion has also been proposed." (PMID 27478827, 2016). "Previous research has shown that obesity is associated with increased serum leptin levels, which may disrupt hypothalamic secretion of thyrotropin-releasing hormone, leading to elevated TSH levels." (PMID 40692879, 2025). "TRH is known as the primary regulator of the hypothalamic-pituitary-thyroid axis, which is important for maintaining energy expenditure and body weight and is active even in states of leptin resistance associated with obesity." (PMID 38577975, 2024). "Obesity and longer duration of hypertension were associated with apparent TRH." (PMID 32343723, 2020). "Studies from USA reported that obesity is a common risk factor for TRH." (PMID 32343723, 2020). "Some related changes in obesity, like the leptin hormone, secreted by adipose tissue, can affect TRH release." (PMID 38526760, 2024). "Age and obesity have been shown to potentially affect the peak prolactin response in the TRH stimulation test." (PMID 39037546, 2024). "Hyperleptinemia, which occurs in obesity-related metabolic disturbances, favors the synthesis of the thyrotropin-releasing hormone via the promotion of the synthesis of the α-melanocyte-stimulating hormone and the activation of the STAT3 transcription factor." (PMID 39202472, 2024). "Although the thesis concerning the increase in TSH in obesity due to the increased production of pro-TRH through the stimulation of the hypothalamus by leptin is plausible, there are certainly other mechanisms that influence (modulate) this relationship." (PMID 35399935, 2022). "Pterostilbene and resveratrol strongly modulate ghrelin and leptin levels while these metabolism‐ and obesity‐related proteins profoundly alter the expression of TRH and TRH‐like peptides." (PMID 35875858, 2022). "Although leptin upregulates TRH expression, sex differences were not reported before and our results point to significant sex differences in TRH expression in obesity." (PMID 34154608, 2021). "Obesity (BMI greater than 30) and longer duration of hypertension since diagnosis were the predictors of TRH." (PMID 32343723, 2020). "The contribution of the leptin-TRH-BAT/lumbar SNA pathway in obesity development and maintenance, in the difficulties of obese individuals in maintaining weight loss, as well as in increased SNA and hypertension, also deserve future consideration." (PMID 32538782, 2020). "Other possible assumptions are that the central hypertonia of the TRH-TSH axis in obesity is an adaptation to chronically increased caloric intake aiming at resetting the basal metabolism at a higher level." (PMID 29412382, 2017). "Little is known about the HPA axis hypertonia involved in obesity and its relation to the TRH-TSH- thyroid axis." (PMID 29412382, 2017). "This is the first study investigating pituitary TSH release in response to exogenous TRH stimulation in a large group of euthyroid children with overweight and obesity." (PMID 27485208, 2016). "In conclusion, baseline serum TSH concentrations are associated with TSH release of the pituitary in response to exogenous TRH stimulation in euthyroid children with overweight and obesity." (PMID 27485208, 2016). "In this study we evaluated the TSH release of the pituitary in response to exogenous TRH stimulation in a large group of children with overweight and obesity." (PMID 27485208, 2016). "Here we describe TSH release of the pituitary in response to exogenous TRH in 73 euthyroid children (39% males) with overweight or (morbid) obesity." (PMID 27485208, 2016).
Obesity (continued). "Moreover, even though some actions of TRH are long-known, such as its role in food intake regulation and the reversal of respiratory depression induced by narcotics, TRH is gaining more importance due to the current epidemics of obesity and fentanyl abuse." (PMID 37446225, 2023). "Interestingly, rats with diet-induced obesity exhibit increased TRH and an upregulation of the HPT axis, despite leptin resistance in the main site of action of leptin, the ArcN." (PMID 32538782, 2020). "Animal models have indicated that hyperthyropinemia seen with obesity may be driven by the enhanced leptin-mediated production of pro-thyrotropin releasing hormone (TRH) or due to impaired feedback due to decreased number of T3 receptors in the hypothalamus." (PMID 32569304, 2020). "Overall, the most favored hypothesis attempting to explain the hyperthyrotropinemia in subjects with obesity is the increased leptin-mediated production of pro-thyrotropin-releasing hormone (TRH)." (PMID 30250485, 2018). "The stimulation of the HPT axis observed in obesity is mainly due to the centrally acting leptin, which regulates the activity of neurons in the hypothalamus and has both direct and indirect effects on thyrotropin-releasing hormone–stimulating thyroid hormone (TRH-TSH) secretion." (PMID 37374075, 2023). "Thus, activated LXR represses TRH levels and induces the orexigenic peptides, which may promote weight gain and obesity." (PMID 29997323, 2018). "However, it is unknown whether TSH release of the pituitary in response to TRH is affected in children with overweight and obesity." (PMID 27485208, 2016). "The observed HPT axis activation at both ages was consistent with diet-induced obesity models and supported by their elevated PVN TRH expression along with absence in MBH peptide accumulation, implying TRH active release." (PMID 41356010, 2025). "Metabolic conditions such as overweight and obesity or pro-inflammatory responses to infection, modulate HPT axis activity by increasing or decreasing hypothalamic TRH expression and release, respectively." (PMID 41356010, 2025). "The increased TRH and TSH in OSAHS with obesity are most likely due to the increased circulating leptin." (PMID 40438137, 2025). "Chronic IP application of TRH to DIO mice reduced food intake and body weight, and improved metabolic parameters related to obesity, such as decreased levels of leptin, triglycerides, or cholesterol." (PMID 38577975, 2024). "Leptin also stimulates TRH and subsequently TSH secretion, thus contributing to mildly elevated TSH concentrations in subjects with obesity." (PMID 39203787, 2024). "Obesity renders ArcN NPY and POMC neurons resistant to leptin, including those that influence PVN TRH neurons." (PMID 36769012, 2023). "With obesity, the direct action of leptin on PVN TRH presympathetic neurons that project to the RVLM may also contribute to hypertension, since knockdown of hypothalamic preproTRH normalized blood pressure in hypertensive diet-induced obese rats." (PMID 36769012, 2023). "TSH is involved in obesity through 1) insulin inhibited deodinase (less T3, high T4), which provides no negative feedback and resulting in high TSH, and 2) leptin is a stimulator of TRH (hypothalamus) which could increase TSH." (PMID 38720938, 2023). "The frequent observation that TSH levels are elevated during obesity is not regarded as a functional defect, but as a mere manifestation of a deranged hypothalamic–pituitary axis or an increase in leptin-induced TRH production and type 2 iodothyronine deiodinase (D2) inhibition in the thyrotrophs." (PMID 37248529, 2023).
Central hypothyroidism (28 papers, 2012 to 2025). A type of hypothyroidism due to an insufficient stimulation of an otherwise normal thyroid gland. "The diminished leptin effect on TRH stimulation is also evident in LEPR deficiency where central hypothyroidism is observed in 13% of cases." (PMID 34177811, 2021). "Indeed, fasted subjects (an example of subjects with reduced leptin signaling) have similar TSH secretion patterns and TRH test results as patients with central hypothyroidism due to IRS4 loss-of-function." (PMID 34566885, 2021). "Because reduced pituitary TSH reserve and impaired thyrotropic stimulation by TRH are included in the pathophysiology of central hypothyroidism in humans, mutated GATA2 may contribute to develop this disorder." (PMID 34576178, 2021). "Murine studies have suggested that impaired TRH signaling may play a role in the central hypothyroidism associated with IGSF1 deficiency." (PMID 26416826, 2015). "A previous study showed that SD caused central hypothyroidism by posttranscriptionally downregulating the synthesis of thyrotropin-releasing hormone (TRH), which might be a compensatory response to an excessive increase in metabolic rate induced by the HPA axis." (PMID 25821467, 2015). "High levels of glucocorticoids can inhibit the pituitary’s response to TRH, leading to central hypothyroidism and affecting thyroid function." (PMID 40385580, 2025). "Excessive glucocorticoid induced central hypothyroidism by reducing thyrotropin-releasing hormone expression and release in the hypothalamus, decreasing TSH secretion in pituitary, as well as inhibiting FT4 and FT3 levels." (PMID 37091746, 2023). "Other investigators have recommended the TSH surge test and the TRH test to be required for the diagnosis of central hypothyroidism." (PMID 35313921, 2022). "Mutations in IRS4 are associated with central hypothyroidism, and the TSH response to the TRH test is blunted in male IRS4 mutation carriers having central hypothyroidism." (PMID 34828419, 2021). "A pathophysiological mechanism of central hypothyroidism due to IRS4 dysfunction incorporating pituitary TRH resistance or defective TSH transcription/post-translational modification is conceivable." (PMID 34566885, 2021). "The most evident consequence of the inappropriate cortisol secretion on thyroid axis activity is a “central hypothyroidism”, which is due to the inhibitory effects of glucocorticoids on TRH and TSH secretion." (PMID 33808529, 2021). "Five male probands from unrelated families with pathogenic variants in the insulin receptor substrate-4 gene (IRS4) (OMIM #300904) had a phenotype consisting of solely X-linked central hypothyroidism and an abnormal TSH response to exogenous TRH." (PMID 34566885, 2021). "Igsf1 knock-out mice have central hypothyroidism, decreased pituitary TRH receptor 1 mRNA expression and impaired responsiveness to TRH compared to healthy littermates." (PMID 34566885, 2021). "Thyrotropin-releasing hormone (TRH) stimulation test confirmed central hypothyroidism with a poor TSH response and normal prolactin secretion." (PMID 28262687, 2017). "Genetic deletion of either the TRH peptide precursor or TRHR1 results in central hypothyroidism and mild growth retardation in mice, consistent with the established role of TRH in thyroid physiology." (PMID 23248581, 2012). "Secondary or central hypothyroidism may arise from pituitary or hypothalamic dysfunctions, or resistance to TRH (thyrotropin-releasing hormone) or TSH (thyrotropin)." (PMID 36983233, 2023). "Until now pathogenic variants of TRH have not been associated with central hypothyroidism in humans, but Trh knock-out mice have been generated." (PMID 34566885, 2021). "However, patients with leptin deficiency and leptin resistance invariably present with central hypothyroidism, and have a different TSH secretion pattern in response to exogenous TRH than patients with IRS4 loss-of-function." (PMID 34566885, 2021).